OR4K1 (olfactory receptor family 4 subfamily K member 1)
Description:
Odorant receptor.
Synonyms: OR14-19
Tractability: Antibody: UniProt places it where antibodies can reach, with medium confidence; UniProt predicts a signal peptide or a membrane-spanning region; its Gene Ontology location is reachable by antibodies, with medium confidence.
Gene: Protein-coding gene on chromosome 14 (19,930,917 to 19,936,757, forward strand). Ensembl gene ENSG00000155249.
Subcellular location: Cell membrane
Pathways (Reactome):
Sensory Perception: Expression and translocation of olfactory receptors
Gene Ontology:
Molecular function: olfactory receptor activity; G protein-coupled receptor activity
Biological process: detection of chemical stimulus involved in sensory perception of smell; G protein-coupled receptor signaling pathway
Cellular component: plasma membrane; membrane
Genetic constraint (gnomAD): Loss-of-function variants: 16 observed, 14.03 expected, observed/expected ratio (o/e) 1.14, 90% interval 0.77 to 1.7. The synonymous counts are far from expectation, so gnomAD's model fits this gene poorly and the ratio says little. Missense variants: 548 observed, 386.95 expected, observed/expected ratio (o/e) 1.42, 90% interval 1.32 to 1.52. Synonymous variants: 181 observed, 136.46 expected, observed/expected ratio (o/e) 1.33, 90% interval 1.17 to 1.5.
Homologues: Orthologues: chimpanzee OR4K1 (97% identical), macaque OR4K1 (94% identical), dog OR4K1B (91% identical), mouse Or4k1 (86% identical), rat Or4k1 (85% identical). Paralogues in human: OR4K15 (63% identical), OR4K14 (62% identical), OR4K13 (60% identical), OR4K5 (60% identical), OR4F5 (59% identical), OR4F4 (59% identical), OR4F17 (59% identical), OR4K17 (59% identical), OR4K2 (59% identical), OR4F6 (54% identical), OR4L1 (54% identical), OR4F15 (52% identical), and 116 more.
Diseases named in the same sentence as OR4K1 in open-access papers:
OR4K1 is named in the same sentence as 1 disease in open-access papers, as found by Europe PMC text mining. Sharing a sentence is not in itself a finding about the gene and the disease.
OR4K1 shares sentences with these, for which no sentence is quoted: bipolar disorder (1 paper).